ENSG00000252870
Gene: Small nucleolar RNA gene on chromosome 11 (115,128,218 to 115,128,373, reverse strand). Ensembl gene ENSG00000252870.
Homologues: Paralogues in human: SNORA59A (44% identical).